ICAM1 (intercellular adhesion molecule 1)
Diseases named in the same sentence as ICAM1 in open-access papers (continued):
Sharing a sentence is not in itself a finding about the gene and the disease.
cancer (continued). "Intercellular and vascular adhesion molecules (ICAM-1 and VCAM-1) play an important role in cancer progression; however, data in the literature are often contradictory." (PMID 34680113, 2021). "Cancer cell intravasation/extravasation is also largely influenced by PFKFB3, as it increases the expression of tumor cell adhesion molecules, VCAM-1, ICAM-1, and E- selectin by NF-κB signaling." (PMID 34831136, 2021). "For patient ID 110, this notably included MAP2K2, KIT, VEGFA, A2M, ICAM1 and PLA2G4A, all of which are involved in cancer development." (PMID 34771574, 2021). "In both of the cancer cell lines, lower levels of TIMP-2 and the intracellular adhesion molecule, ICAM-1, were noted." (PMID 34829982, 2021). "Both embryo JEG-3 and cancer MCF-7 cells expressed high sLex, CD47, CAMs, while both endometrial RL95-2 and endothelial HUVECs exhibited high integrins and ICAM-1." (PMID 34556175, 2021). "These cytokines have been identified to be directly or indirectly responsible for cancer progression through remodeling of ECM by upregulating the expression of molecules such as MMP2, MMP3, MMP9, MMP10, MMP13, PLAU, ICAM1 and VCAM1." (PMID 34946170, 2021). "As a result, CXCL10, IGF1, MMP3, MMP1, ICAM1, and IL-13 levels were markedly up-regulated within NPC samples relative to the non-carcinoma samples (P < 0.05)." (PMID 34544905, 2021). "Integrins (such as αvβ3 and β5 integrins), ligand sialyl Lewis, and endothelial receptors (ICAM-1,VCAM-1) are also widely reported to contribute to the adhesion of cancer cells to endothelia in and expressed on several cancer cells’ surface." (PMID 33379338, 2020). "ICAM1, ITGA3 and MMP1 are involved in the remodeling of the extracellular matrix, and their expression is known to be aberrant in some cancers." (PMID 32899628, 2020). "Cell adhesion molecules, such as ICAM-1 and VCAM-1, are involved in cancer growth, migration from primary sites to distant organs, and adhesion to ECs." (PMID 32466580, 2020). "The roles of MMP-2, MMP-9, ICAM-1, and VEGF are well known in the invasion and angiogenesis of cancer." (PMID 32455624, 2020). "Other secreted-proteins, such as MPS-1, ICAM-1, and PLOD2, have also been validated as critical downstream effectors of leptin in cancers." (PMID 33371368, 2020). "AIM suppressed the TNF-α effects on the NF-κB-regulated proteins involved in cancer cell proliferation (COX-2, C-myc), invasion, and angiogenesis (MMP-2, MMP9, ICAM-1, and VEGF)." (PMID 32455624, 2020). "According to previous studies, VEFG-1, ICAM-1, TGF-β2, MMP-1, and MMP-9 are key genes involved in the regulation of cancer cell metastasis and invasion." (PMID 32210104, 2020). "AIM suppressed TNF-α effects on the NF-κB-regulated proteins involved in cancer cell proliferation (COX-2, and C-myc), invasion, and angiogenesis (MMP-2 and MMP9, ICAM-1 and VEGF)." (PMID 32455624, 2020). "ICAM-1, also known as CD54, is a cell transmembrane protein that is commonly expressed on the surface of leukocytes, endothelial cells and some types of cancer cells." (PMID 31164960, 2019). "In the process of cancer metastasis, MT1-MMP, MMP-9, uPAR, ICAM-1, and Cox-2 are responsible for cell migration, invasion, and adhesion." (PMID 31766230, 2019). "The adhesion molecules ICAM-1 and VCAM-1 are mediating the cell adhesion of cancer cells, lymphocytes and other cells to the vascular endothelium." (PMID 31731625, 2019). "In particular, two networks directly related to cancer presented MDM2, ICAM1, and FTH1 as central nodes." (PMID 30925701, 2019). "In conclusion, our results suggested the important roles of ITGA2, FN1, ICAM1, TIMP1 and CDH2 in the progression of PTC via various cancer-related pathways." (PMID 30414611, 2018). "ICAM-1 is a ligand for LFA-1, which is expressed on a number of cell types, including T cells, APCs and some cancer cells." (PMID 30348199, 2018).
cancer (continued). "Integrins such as vascular cell adhesion molecule 1 (VCAM-1) and intercellular adhesion molecule 1 (ICAM-1) have been shown to be involved in metastasis and cancer cell migration." (PMID 30105032, 2018). "For instance, NF-κB activation was required for the transcription of a group of adhesion molecules including endothelial-leukocyte adhesion molecule-1 (ELAM-1) and intercellular adhesion molecule-1 (ICAM-1), which facilitate the extravasation of cancer cells." (PMID 29361914, 2018). "Our data showed that the interaction of cancer and endothelial cells increases COX-2, IL-8, ICAM1 and VCAM1 mRNA levels of HUVECs." (PMID 28173828, 2017). "Subsequently, we performed FACS detection of CAMs, and the results showed that cancer group cells had increased CD18 (ITGB2), CD106 (VCAM-1), and CD31 (PECAM-1), with decreased CD54 (ICAM-1)." (PMID 28350008, 2017). "Subsequently, p-STAT3 can induce the downstream target genes, such as CCL2, CCL5, ICAM-1, SNAI1, chitinase-3-like 1 (CHI3L1), FBJ murine osteosarcoma viral oncogene homolog (FOS), and Skp2, that promote various cellular processes for cancer progression." (PMID 28157698, 2017). "Resveratrol blocked cancer cell adhesion to endothelial cells through inhibition of ICAM-1 expression; however, they observed that this downregulation of ICAM-1 expression was due to suppression of NF-κB activation." (PMID 27834913, 2016). "In order to elucidate the potential role of lovastatin in cancer gene expression, lovastatin-treated HuH-28 and RBE cells were harvested and qPCR was used to quantify expression of integrin β3, TGFβ1, ICAM-1, and COX-2." (PMID 26517522, 2016). "The expression of ICAM-1 and VCAM-1, which are regulated by the transcription factor NF-κB, in endothelial cells initiates the adhesion of cancer cells and monocytes to the endothelium." (PMID 26690142, 2015). "Recently, soluble forms of adhesion molecules, including ICAM-1 and VCAM-1, have been found in the serum of cancer patients, in the supernatant of cytokine-activated endothelial cells and in the culture medium of CRC cell lines." (PMID 26690142, 2015). "ICAM-1 and VCAM-1 are two important cell surface adhesion molecules that are mainly expressed in endothelial cells to modulate the immune process and cancer cell adhesion to the endothelium." (PMID 26690142, 2015). "Resistin has been indicated to induce ICAM-1 and VCAM-1 expressions through transcription factor NF-κB in endothelial cells and to initiate the cancer cells and monocyte adhesion." (PMID 24555415, 2014). "Previous reports have described that intercellular adhesion molecule-1 (ICAM-1) and matrix metalloproteinase 9 (MMP-9) are involved in cancer cell adhesion, invasion, and migration, which contribute to cancer metastasis." (PMID 24901215, 2014). "Owing to the basal/negligible level of VAP-1 and ICAM-1 in TMNK-1 only and all HUVECs cultures, these surface molecules plausibly affected the cancer cell adhesion minimally, which explained the minimum effect of the blocking." (PMID 24900957, 2014). "To confirm this, we investigated cancer cell adhesion in the cultures by blocking two surface molecules of ECs: VAP-1 and ICAM-1." (PMID 24900957, 2014). "To test the specific adhesion between cancer cells and ICAM-1 molecules, we carried out force spectroscopy experiments between a cancer cell attached to the tip of an AFM cantilever and immobilized ICAM-1 molecules on a glass dish." (PMID 24857933, 2014). "Among TMNK-1|gel, TMNK-1 + 10T1/2|gel, HUVECs|gel, and HUVECs + 10T1/2|gel, only in the TMNK-1 + 10T1/2|gel adhesion of cancer cells decreased upon blocking of VAP-1 and ICAM-1." (PMID 24900957, 2014). "A combination of B7.1, LFA-3 and ICAM-1 (TRICOM) has been assessed both pre-clinically and clinically with a pox-viral platform against a number of different cancer models." (PMID 25140889, 2014).
cancer (continued). "Apart from IL8, the co-regulation between NF-κB and AP1, CEBPB or STAT3 for genes IL1B, ICAM1, IL6, PTGS2, and SAA1 in the TF regulatory networks is consistent with previous observation in HNSCC or other cancer cells." (PMID 24069219, 2013). "The roles of MMP-2, MMP-9, ICAM-1, and VEGF in invasion, adhesion, and angiogenesis of cancer are well known and regulated by NF-κB." (PMID 23864892, 2013). "It has been reported that ionizing radiation up-regulated immunological cell surface molecules such as ICAM-1, CEA, and mucin-1 on human cancer cells in vitro." (PMID 24131485, 2013). "Our results demonstrated that 5 of the 6 up-regulated mRNAs in “HTLV-1 infection pathway” increased (ICAM1, WNT2B, MYC, HLA-F and TGF-β1) and 3 of the 5 down-regulated mRNAs in “Pathways in cancers” decreased (CDH1, PTENP1, HSP90AA1)." (PMID 24367666, 2013). "Our results showed that the MFAT secretome inhibited the production of MCP-1 and RANTES, significantly reduced the expression of ICAM-1 (Intercellular Adhesion Molecule 1) on U-937 macrophages, and had no impact on the proliferation of normal or cancer cells." (PMID 41834645, 2026). "The depletion of ICAM-1 in T-cells led to a lack of immune infiltration in tumors with poor cancer control." (PMID 40071851, 2025). "These proteins, including ICAM-1, SPPL2A, CD276, and CD44, may help the cancer cells stick together, spread, and avoid the immune system." (PMID 40805206, 2025). "Additionally, these EVs effectively reduced the expression levels of intercellular adhesion molecule 1 (ICAM1) and the cysteine protease cathepsin, two key mediators in the process of cancer progression." (PMID 39195369, 2024). "Similarly to ICAM-1, VCAM-1 acts in the immune-endothelial communication system, contributing to inflammatory and immune processes and cancer metastasis." (PMID 38785560, 2024). "ICAM-1 is also highly expressed by various cancer cells, and ICAM-1 antibodies conjugated with anticancer drugs have recently been evaluated in vivo as novel approaches to cancer treatment." (PMID 39329738, 2024). "Given that PET radiotracers are highly clinically translatable, further optimization of ICAM-1-based PET radiotracers is warranted for an effective noninvasive strategy to guide combinational RT in patients with cancer to facilitate precision therapy." (PMID 38169608, 2024). "ICAM-1 participates in cell migration and proliferation via NFκB, NPM1, Pho/JNK, GTP/LFA-1/JAK/STAT3, and Ras/RAF/MEK/ERK activates the Raf/MEK/ERK pathway which is responsible for cancer cell proliferation and migration." (PMID 39149564, 2024). "Evidence supports that ICAM1 binds to MUC1, which is known to be overexpressed in cancer cells and cancer stem cells, and CD80 binds to CTLA4, which is an immunosuppressive marker that is also expressed in cancer stem cells." (PMID 38903193, 2024). "This posttranslational modification allows type-1 matrix metalloproteinases (MT1-MMP) to interact with ICAM-1 in endothelial cells and to cleave the ICAM-1 ectodomain, resulting in soluble (s)ICAM-1, a process that seems important for leukocyte TEM and cancer metastasis." (PMID 38391953, 2024). "In addition, since the cancer cell cluster C6 was characterized by concurrent enrichment of liver CSCs markers CD24, CD47 and ICAM1, we further sought to confirm the interaction between cluster C6 cancer cells and M2-like TAMs using TCGA-LIHC cohort." (PMID 38169544, 2024). "Intercellular adhesion molecule-1 (CD54) was identified as an up-regulated candidate for further investigation, and its high expression in cancer tissues of EC patients was validated using immunohistochemistry, real-time quantitative PCR (RT-qPCR), and western blot analyses." (PMID 37966470, 2023).
cancer (continued). "The activity of CD8+ T cells was evaluated by measuring IFN‐γ release; IFN‐γ production in CD8+ T cells was significantly abated in CT26 cells than in 4T1 cells after ICAM‐1 depletion, suggesting that ICAM‐1 in CT26 cancer cells positively regulates CD8+ T cell activation." (PMID 37097643, 2023). "The statistical analysis showed that CCA patients with ICAM1+ expression in cancer tissues was as high as 37.2%, while there was no expression of ICAM1 in the normal bile duct tissues and liver tissues in the corresponding para-cancerous tissues." (PMID 37717087, 2023). "The strategies include targeting vascular endothelial growth factor/receptors, αvβ3 integrin receptors overexpressed on endothelial cells in various types of cancer, as well as vascular cell adhesion molecule-1 (VCAM-1) and intercellular adhesion molecule-1 (ICAM-1)." (PMID 37376203, 2023). "The cancer-induced increase of integrin expression in EC as well as the reciprocal expression of the integrin ligands, VCAM-1 and ICAM-1, on the surface of the cancer cells is the opposite to what is described for the interactions between EC and ALL cells as well as EC and normal lymphocytes." (PMID 37173970, 2023). "Double strand breaks in cancer cells occur spontaneously, a phenomenon termed ‘self-inflicted DNA DSBs’ which sustain tumorigenesis and maintain the expression/secretion of main inflammatory factors (IL6, IL8, GROα, ICAM-1, Cox-2)." (PMID 36982207, 2023). "Moreover, ICAM1 and MMP2 presented higher expressions of COAD cancer tissues than in normal tissues." (PMID 37575276, 2023). "Then, the aim of this study was also to test whether PD can modulate the expression of adhesion molecules, such as ICAM-1, VCAM-1, and E-selectin, induced in HUVECs by the SN of LPS-stimulated HT-29 cancer cells." (PMID 35955576, 2022). "This crucial CD103-E-cadherin interaction is required for polarized exocytosis of lytic granules, mostly in the absence of ICAM-1 expression on cancer cells, leading to target cell death." (PMID 36428727, 2022). "Although ICAM1 appears to be required for the elicitation of an efficient CD32-CR T cell anti-cancer activity its expression is non-sufficient for the following considerations." (PMID 36241426, 2022). "Therefore, we confirmed that STAT3 can regulate ICAM-1 expression by forming a positive feedback loop in CRC, identical to other cancer types." (PMID 35487888, 2022). "Previously, we studied the role of ICAM-1 in various cancers; however, its role and mechanism in CRC has not been fully elucidated." (PMID 35487888, 2022). "Regarding infectivity, cancer cells may also overexpress different surface receptors, such as CD46, ICAM-1, CD55, CD155 or integrins, allowing OVs to infect cancer cells." (PMID 35493490, 2022). "Strikingly, however, in vivo OVA E0771 killing by CTLs did not also require the presence of ICAM-1 on the cancer cell targets." (PMID 35911772, 2022). "In the process of extravasation, adhesive molecules, such as E-selectin, vascular cell adhesion molecule 1 (VCAM-1), intercellular adhesion molecule 1 (ICAM-1), or very late antigen-4 (VLA-4), are expressed to ensure interactions between cancer cells and the BBB." (PMID 35884446, 2022). "MTCAF-derived ICAM-1 has double roles: It not only regulates the growth and migration of MTCAFs by mediating the expression of IL6 and IL8 in MTCAFs but also can promote the proliferation and invasion of cancer cells." (PMID 36016615, 2022). "Furthermore, UA treatment reduces the expression of the adhesion molecule, intercellular adhesion molecule-1 (ICAM-1), which is another important regulator of cancer metastasis." (PMID 34439409, 2021). "Moreover, in mass spectrometry analysis performed on media collected from restimulated CD4+ T cells grown with cancer cells, the secreted cytokines and other factors such as IL-8, IL-6, CXCL1, and ICAM1 were found." (PMID 34439305, 2021).
cancer (continued). "These include vimentin and/or ICAM-1, whose expression was elevated in MAs-treated cancer and normal cells." (PMID 33921783, 2021). "We thus propose that MAPK10 and ICAM1 are potential prognostic factors and targets for therapy in HCC, warranting further research of connections between these molecules, immune response and cancer cell survival." (PMID 34408980, 2021). "Moreover, previous studies have shown that downregulation of VCAM1, ICAM1, and CDH2 can inhibit cancer cell proliferation and migration." (PMID 34098960, 2021). "Indeed, at very low concentrations (3 μM), CBD induced intracellular adhesion molecule 1 (ICAM-1) and TIMP1 levels, decreasing cellular migration and increasing cancer cell lysis." (PMID 31979368, 2020). "Moreover, after receiving cancer treatment radioactivity in lung cells diminished and cancer promoting factors declined (VEGFR2, ICAM-1, bFGF, KC, TNF-α, IL-6, IL-12, IL-10 and IL-13) showing a diminution of metastatic competency of the exosomes." (PMID 32570802, 2020). "Moreover, some antibodies target only specific cancer types (e.g., PSMA-, HER2-expressing tumors) or lack cancer-specificity because their targets are expressed also by other cells (e.g., CD133, VCAM-1, ICAM-1)." (PMID 32260071, 2020). "Cancer cells treatment with leptin induces the secretion of both intracellular adhesion molecule 1 (ICAM-1) and RANKL and enhances tumor-induced osteolysis in vivo, suggesting a potential role for leptin in osteoclast-like giant cell formation in a cancer context." (PMID 33203195, 2020). "Standard therapy may present some detrimental aspects such as tissue damage, hypoxia and cancer cell apoptosis through the release of proinflammatory cytokines such as TNF-alpha, granulocyte-colony stimulating factor (G-CSF), CXCL12, CCL2-4 and ICAM1." (PMID 32708431, 2020). "We found that AIM suppressed NF-κB activation induced by TNF-α in MCF-7 cells, and the upregulation of NF-κB-regulated genes (COX-2; MMP-2, MMP-9, and VEGF) involved in cancer cell proliferation (COX-2, C-myc, Cyclin-D1), and invasion, adhesion, and angiogenesis (MMP-2, MMP-9, ICAM-1, VEGF)." (PMID 32455624, 2020). "Endothelial selectins, such as: P-selectin, E-selectin, and the intercellular adhesion molecules: Intercellular Adhesion Molecule 1 (ICAM-1), Vascular cell adhesion molecule 1 (VCAM-1) and their ligands, have been related to immune cell and cancer cell adhesion to the vasculature." (PMID 31382462, 2019). "ICAM1 was previously reported to contribute to the activation of not only NK cells but also CTLs, and NANOG expression was shown to induce CTL resistance in cancer cells." (PMID 31619256, 2019). "When it comes to cancers originating from the gastrointestinal tract, their improved adhesion to senescent PMCs resulted from p38 MAPK- and AP-1-dependent overproduction of surface ICAM-1." (PMID 28956065, 2018). "Various cell adhesion molecules on the endothelium, such as intercellular adhesion molecule 1 (ICAM-1), vascular cell adhesion protein (VCAM-1), E-selectin or N-cadherin as well as integrins expressed on cancer cells have been reported to mediate cell adhesion of cancer cells onto endothelial cells." (PMID 30204757, 2018). "Currently, there are no evidences of any open assay using BI-505 or other anti-ICAM-1 mAb as single agent or in combination to treat cancer." (PMID 30258446, 2018). "Although, lack of data makes debatable whether T-cell egress from tumors is a meaningful phenomenon in cancer immunology, our results suggest that modulation of LFA-1/ICAM-1 to implement T-lymphocyte egress from malignant tissue is a possibility." (PMID 30258446, 2018). "Taken together, these data identify membrane-bound ICAM-1 as a crucial regulator of contractile and proinvasive CAF activities, and highlight a novel potential therapeutic target for the procarcinogenic activity of CAF in cancer development." (PMID 27901489, 2017).